KCNG4 (potassium voltage-gated channel modifier subfamily G member 4)
Description:
Potassium channel subunit that does not form functional channels by itself (Probable). Reduces the deactivation rate. Modulates the threshold for activation by shifting by approximately 20 mV in hyperpolarizing direction. Markedly changes the inactivation by shifting the voltage dependence of inactivation by approximately 40 mV in hyperpolarizing direction. Acceleratee activation and enhances the time course of activation.
Synonyms: Kv6.4; KV6.3
Tractability: Small molecule: an approved drug acts on it; it belongs to a druggable protein family. Antibody: UniProt places it where antibodies can reach, with high confidence; its Gene Ontology location is reachable by antibodies, with high confidence; UniProt predicts a signal peptide or a membrane-spanning region; the Human Protein Atlas places it where antibodies can reach.
Gene: Protein-coding gene on chromosome 16 (84,218,657 to 84,240,012, reverse strand). Ensembl gene ENSG00000168418.
Subcellular location: Cell membrane
Subcellular location (Human Protein Atlas): Plasma membrane; Nucleoplasm
Pathways (Reactome):
Neuronal System: Voltage gated Potassium channels
Gene Ontology:
Molecular function: potassium channel regulator activity; transmembrane transporter binding; monoatomic ion channel activity; voltage-gated potassium channel activity
Biological process: regulation of potassium ion transmembrane transport; regulation of potassium ion transport; action potential; potassium ion transmembrane transport; monoatomic ion transport; potassium ion transport; protein homooligomerization; transmembrane transport
Cellular component: plasma membrane; voltage-gated potassium channel complex; membrane
Genetic constraint (gnomAD): Loss-of-function variants: 34 observed, 30.72 expected, observed/expected ratio (o/e) 1.11, 90% interval 0.84 to 1.47. The upper end of that interval is the gene's LOEUF score, 1.47, which puts it in group 6 of 6, group 1 being the genes least tolerant of losing a copy. Missense variants: 879 observed, 731.05 expected, observed/expected ratio (o/e) 1.2, 90% interval 1.14 to 1.27. Synonymous variants: 375 observed, 323.74 expected, observed/expected ratio (o/e) 1.16, 90% interval 1.06 to 1.26.
Homologues: Orthologues: chimpanzee KCNG4 (98% identical), macaque KCNG4 (97% identical), pig KCNG4 (83% identical), guinea pig KCNG4 (81% identical), dog KCNG4 (80% identical), mouse Kcng4 (80% identical), rat Kcng4 (79% identical), rabbit KCNG4 (79% identical), tropical clawed frog kcng4 (65% identical), zebrafish kcng4a (59% identical), zebrafish kcng4b (53% identical). Paralogues in human: KCNG1 (55% identical), KCNG2 (49% identical), KCNB2 (35% identical), KCNG3 (34% identical), KCNS3 (30% identical), KCNS2 (29% identical), KCNS1 (29% identical), KCNV1 (29% identical), KCNF1 (28% identical), KCNV2 (28% identical), KCNC3 (27% identical), and 19 more.
Diseases named in the same sentence as KCNG4 in open-access papers:
KCNG4 is named in the same sentence as 10 diseases in open-access papers, as found by Europe PMC text mining. Sharing a sentence is not in itself a finding about the gene and the disease. The quoted sentences say what the papers report.
migraine (4 papers, 2021 to 2025). "Loss-of-function Kcng4 mutations in humans have been associated with reduced pain sensitivity in migraine and labor during pregnancy, likely due to altered function of Kv2.1/Kv6.4 heterotetramers and disrupted excitability." (PMID 41279724, 2025). "The signalling pathways leading to migraines have not been fully understood, but neuronal voltage-gated ion channels, such as KCNG4, have been linked to this pathology." (PMID 39201645, 2024). "Kcng4 encodes a subunit of a potassium voltage-gated channel that has been identified as potentially linked to migraine (Lafrenière and Rouleau, 2012)." (PMID 34955765, 2021). "Our work shows that the migraine-related gene Kcng4 is actually expressed from r2 to r9, which correspond to the principal, oral and interpolar subnuclei, which also have recently been proposed to play a role in migraine." (PMID 34955765, 2021).
angiosarcoma (1 paper, 2016). A malignant tumor arising from the endothelial cells of the blood vessels. "Notably, expression of several potassium channels is modified in bladder cancer vessels vs controls (KCNC4, KCNG4, KCNS2) and in angiosarcoma vs controls (namely KCNJ16, KCNQ2, KCNJ15, KCNJ12, KCNJ1)." (PMID 27716384, 2016).
cognitive abnormalities (1 paper, 2020). "However, we found that women carrying the rare allele KCNG4 managed nulliparous labor without analgesics and had higher experimental pain thresholds but were otherwise healthy without any psychological or cognitive abnormalities." (PMID 32697988, 2020).
latent infection (1 paper, 2025). "The downregulated DETs of Sept4, Kcng4, Unc13c, and Prkcg in the WH6 group, which are related to synaptic transmission, and Ndrg2 and Arc in the LHG group, which are related to neurodegenerative diseases, were selected to be the key candidates in the latent infection phase." (PMID 40420177, 2025).
lung carcinoma (1 paper, 2023). "To determine the role of KvS subfamilies in NSCLC, we explored the lung cancer datasets from The Cancer Genome Atlas (TCGA) to inquire expression levels of KCNF1 (Kv5.1), KCNG4 (Kv6.4), KCNV2 (Kv8.2), and KCNS1 (Kv9.1)." (PMID 36385523, 2023).
KCNG4 also shares sentences with these, for which no sentence is quoted: bladder cancer (1 paper); fragile X syndrome (1); hydatidiform mole (1); Hydrocephalus (1); neurodegenerative disease (1).